C12orf75 (chromosome 12 open reading frame 75)
Synonyms: OCC-1; OCC1; AGD3
Tractability: PROTAC: ubiquitination databases record sites on it.
Gene: Protein-coding gene on chromosome 12 (105,235,290 to 105,396,097, forward strand). Ensembl gene ENSG00000235162.
Subcellular location (Human Protein Atlas): Vesicles
Genetic constraint (gnomAD): Loss-of-function variants: 0 observed, 0.35 expected, observed/expected ratio (o/e) 0, 90% interval 0 to 1.86. That is too few expected variants to judge how well the gene tolerates losing a copy. Missense variants: 19 observed, 12.15 expected, observed/expected ratio (o/e) 1.56, 90% interval 1.07 to 1.93. Synonymous variants: 13 observed, 5.84 expected, observed/expected ratio (o/e) 2.22.
Homologues: Orthologues: macaque C11H12orf75 (97% identical), pig C12orf75 (94% identical), dog C10H12orf75 (89% identical), mouse 1500009L16Rik (83% identical), rat C7h12orf75 (79% identical).
Diseases named in the same sentence as C12orf75 in open-access papers:
C12orf75 is named in the same sentence as 20 diseases in open-access papers, as found by Europe PMC text mining. Sharing a sentence is not in itself a finding about the gene and the disease. The quoted sentences say what the papers report.
leukemia (2 papers, 2021 to 2025). A malignant (clonal) hematologic disorder, involving hematopoietic stem cells and characterized by the presence of primitive or atypical myeloid or lymphoid cells in the bone marrow and the blood. "C12orf75 was highly expressed in cervical cancer, colorectal cancer, esophageal cancer, head and neck cancer, kidney cancer, leukemia, liver cancer, and ovarian cancer." (PMID 34074799, 2021). "Several of the top 20 APL super enhancers are linked to genes known to have functional roles in leukemia, for example RNF216, FSCN1, FNDC3B, HSP90B1, C12orf75, and JARID2, among them, JARID2 is a hematopoietic tumor suppressor through recruiting PRC2 to repress self-renewal pathways." (PMID 41168841, 2025).
breast carcinoma (1 paper, 2021). "In related research in human cancers, C12orf75 was only reported in colorectal cancer and breast cancer." (PMID 34074799, 2021). "Similarly, C12orf75 induced apoptosis in the breast cancer cell line (MCF7)." (PMID 34074799, 2021). "Similarly, C12orf75 was reported to promote the apoptosis of breast cancer cells." (PMID 34074799, 2021).
colorectal cancer (1 paper, 2021). A primary or metastatic malignant neoplasm that affects the colon or rectum. "In different colorectal cancer studies, C12orf75 was found to either promote or inhibit cancer cell growth." (PMID 34074799, 2021). "C12orf75 was found to inhibit CACO-2 proliferation, and it promoted tumor cell survival in the SW480 (Wnt+) derived from colorectal cancer." (PMID 34074799, 2021). "However, C12orf75 seemed to have the opposite effect in SW480 cells (Wnt–), instead increasing apoptosis of colorectal carcinoma cells." (PMID 34074799, 2021).
hepatocellular carcinoma (1 paper, 2021). A malignant tumor that arises from hepatocytes. "The knockdown of C12orf75 in hepatocellular carcinoma cells suppressed the proliferation, migration, and invasion and arrested the cell cycle." (PMID 34074799, 2021). "RNA interference was used to verify the influence of C12orf75 knockdown on the biological phenotype of hepatocellular carcinoma cells." (PMID 34074799, 2021).
liver cancer (1 paper, 2021). An epithelial or non-epithelial malignant neoplasm that arises from the liver. "Liver cancer cells were blocked in the S phase by knockdown of C12orf75 and it also shows that C12orf75 presumably involved in DNA replication or DNA damage check." (PMID 34074799, 2021). "The RNA expression of C12orf75 was positively correlated with the histological tumor grade in the TCGA liver cancer dataset (p = 0.0026)." (PMID 34074799, 2021). "Downregulation of the RNA expression of C12orf75 suppressed the proliferation ability of the liver cancer cells 97H and LM3 according to the CCK8 staining results." (PMID 34074799, 2021). "Above all, the high expression of C12orf75 was confirmed in liver cancer cell lines and HCC patient samples." (PMID 34074799, 2021). "C12orf75 silencing also clearly reduced the migration and invasion ability of 97H and LM3 liver cancer cells." (PMID 34074799, 2021).
ovarian carcinoma (1 paper, 2021). A malignant neoplasm originating from the surface ovarian epithelium. "The results suggested that changes in the C12orf75 gene mainly occur in prostate sarcoma and ovarian cancer, but there were only 43 cases representing less than 0.1% of patients." (PMID 34074799, 2021).
prostate adenocarcinoma (1 paper, 2021). "Meanwhile, decreased expression of C12orf75 was in prostate adenocarcinoma (PRAD)." (PMID 34074799, 2021).
renal papillary cell carcinoma (1 paper, 2021). "The increased expression of C12orf75 was related with a poor prognosis in urothelial bladder carcinoma and hepatocellular liver carcinoma, but it was surprisingly converse in renal papillary cell carcinoma." (PMID 34074799, 2021). "C12orf75 has potential as a prognostic biomarker and therapeutic target for molecularly targeted drugs in urothelial bladder carcinoma, hepatocellular liver carcinoma, and renal papillary cell carcinoma." (PMID 34074799, 2021). "This is the first report C12orf75 has potential as a prognostic biomarker and therapeutic target for molecularly targeted drugs in urothelial bladder carcinoma, hepatocellular liver carcinoma, and renal papillary cell carcinoma." (PMID 34074799, 2021).
urothelial bladder carcinoma (1 paper, 2021). "In urothelial bladder carcinoma and hepatocellular liver carcinoma, we observed positive correlations between the expression of C12orf75 and the infiltration of immune cells, including B cells, CD8+ T cells, CD4+ T cells, macrophages, neutrophils, and dendritic cells." (PMID 34074799, 2021).
tumor (3 papers, 2019 to 2021). "The histological tumor grade was positively correlated with the expression of C12orf75 (p < 0.001), and increased expression of C12orf75 was positively associated with tumor progression after treatment (p = 0.0025)." (PMID 34074799, 2021). "Based on the available studies, C12orf75 appears to play dual roles, either promoting or inhibiting tumor progression depending on the cancer type, but there was a lack of broader studies in different human cancers." (PMID 34074799, 2021). "To understand the influence of variety C12orf75 expression on the biological phenotype of tumor cells, we conducted GO pathway enrichment analysis of genes." (PMID 34074799, 2021). "We conducted GO analysis and found pathways through which C12orf75 possibly influences tumor biological phenotype in conjunction with the TCGA database." (PMID 34074799, 2021). "Overall, the upregulation of C12orf75 expression promoted tumor progression in BLCA, LIHC, and UVM, while it seemed to be related with a better prognosis in KIRP patients." (PMID 34074799, 2021). "In this study, in areas with maintained cortical structure, C12orf75 was found staining the perikarya of pyramidal cells, and in tumor areas the protein often disclosed enlarged or giant cells." (PMID 31006040, 2019). "C12orf75 may influence the cancer prognosis by changing the tumor immune infiltration and the status of tumor DNA replication." (PMID 34074799, 2021). "Additionally, we were unable to retrieve any published research that clarifies the function of C12orf75 in tumor immunity." (PMID 34074799, 2021). "Our results suggest that C12orf75 plays an important role in immune cell infiltration and recruitment of antigen presenting cells in the tumor microenvironment, which may directly affect the prognosis and survival of patients." (PMID 34074799, 2021). "However, C12orf75 had no substantial association with the infiltration levels of tumor-associated macrophages in KIRP." (PMID 34074799, 2021). "In the mRNA group, ZIC5, C12orf75, C1QL1, TMEM74, and GNAZ were significantly upregulated in tumor tissues compared to the adjacent control; PZP and FAM65C were significantly downregulated compared to the adjacent control." (PMID 31156698, 2019). "From a clinicopathological viewpoint, the expression of C12orf75 had a negative correlation with the tumor size and tumor invasion status (p = 0.043 and p = 0.034, respectively)." (PMID 34074799, 2021).
cancer (2 papers, 2021 to 2023). A tumor composed of atypical neoplastic, often pleomorphic cells that invade other tissues. "The systemic analysis of C12orf75 in the present study was performed in various types of cancer, which clarified that C12orf75 upregulation was considerably associated with the worse survival and prognosis of patients with BLCA or LIHC." (PMID 34074799, 2021). "Based on previous research, the association between expression of C12orf75 and promoter methylation in different cancer types was explored using DNMIVD." (PMID 34074799, 2021). "Thus, there was a low incidence of C12orf75 mutations in the cancer genome." (PMID 34074799, 2021). "The differential expression of chromosome 12 open reading frame 75 (C12orf75) was correlated with tumorigenesis and cancer progression." (PMID 34074799, 2021). "To better understand the influence of C12orf75 expression on the prognosis in cancer types that showed a distinct correlation, we analyzed various clinicopathological features in selected cancers in the TCGA database using the “ggpubr” R package." (PMID 34074799, 2021). "And, in other datasets, the hazard ratio was analyzed between the prognosis of patients with diverse cancers and the expression of C12orf75 by PrognoScan." (PMID 34074799, 2021). "Here, we studied the expression levels of C12orf75 and investigated its prognostic value in various cancers across distinct datasets including ONCOMINE, PrognoScan, GEPIA, and TCGA." (PMID 34074799, 2021). "The differential expression of chromosome 12 open reading frame 75 (C12orf75) is closely related with cancer progression." (PMID 34074799, 2021). "In recent years, C12orf75 was found to have a close relationship with human cancers." (PMID 34074799, 2021). "To investigate the correlation between C12orf75 expression and patient prognosis in human cancers, we applied the "survival" R package to investigate the relationship between the C12orf75 expression data of various cancers in TCGA and the patients' survival time." (PMID 34074799, 2021). "The results suggested that C12orf75 is overexpressed in most human cancers." (PMID 34074799, 2021). "C12orf75 showed increased expression in most tested human cancers." (PMID 34074799, 2021). "Thus, further research should verify the role of C12orf75 in other cancers, and the levels of immune infiltration should be verified by single-cell RNA sequencing to better reflect the actual infiltration of immune cells." (PMID 34074799, 2021). "Therefore, we conducted a comprehensive investigation of the C12orf75 gene in distinct cancers based on TCGA and the GEO database." (PMID 34074799, 2021). "Further, unknown reasons for the change of C12orf75 expression in different cancers needed further study." (PMID 34074799, 2021). "Thus, C12orf75 might play a cancer-promoting role in the tumorigenesis and progression of HCC." (PMID 34074799, 2021). "At the last follow-up, the expression of C12orf75 was considerably higher in patients with cancer than patients without cancer (p = 0.0067)." (PMID 34074799, 2021). "At the last follow-up, the expression of C12orf75 was higher in patients with cancer than patients without cancer (p < 0.001)." (PMID 34074799, 2021).
C12orf75 also shares sentences with these, for which no sentence is quoted: infection (2 papers); cervical cancer (1); colon carcinoma (1); cystic fibrosis (1); endometriosis (1); esophageal cancer (1); head and neck cancer (1); kidney cancer (1); prostate sarcoma (1).